TNF (tumor necrosis factor)
Diseases named in the same sentence as TNF in open-access papers (continued):
Sharing a sentence is not in itself a finding about the gene and the disease.
Obesity (continued). "One possible mechanism for this is the key role of obesity in increasing serum levels of tumor necrosis-α (TNF-α) factor and free fatty acids, which is accompanied by increased oxidative stress." (PMID 23497678, 2012). "In the obesity-associated elevation of PAI-1, evidence also points to TNFα as an important regulator of PAI-1 expression in adipose tissue." (PMID 22745783, 2012). "Our data showed that the body weight was increased by 21% in TNF−/− mice fed with HCD versus only 11% in the TNF-WT mice subjected to the same regime, therefore suggesting a protective effect of TNFα in diet-induced obesity." (PMID 23125848, 2012). "The expression of adipokines, such as leptin, is also modified in obesity and diabetes and there is a strong correlation between serum leptin and TNFα levels." (PMID 23125848, 2012). "HFD-induced obesity led to a decrease in TNF-α production by peritoneal macrophages stimulated with LPS, conversely, the administration of B. uniformis CECT 7771 increased TNF-α production and phagocytosis." (PMID 22844426, 2012). "Since TNFα levels were increased under diet-induced obesity conditions in both adipose tissue depots, TNFα secretion was measured from APP stimulated adipocytes." (PMID 22276186, 2012). "A key role for TNF-α in obesity-related insulin resistance was identified when TNF-α or TNF-α receptors were deleted in both diet-induced obese mice and leptin-deficient ob/ob mice, which resulted in significantly improved insulin sensitivity." (PMID 22110480, 2012). "Circulating TNF-α and MCP-1 are increased in obesity and have been implicated as causative factors in obesity-associated insulin resistance and the development of type 2 diabetes." (PMID 21589925, 2011). "It is now well established that in obesity, insulin resistance is, at least in part, mediated by cytokines produced in adipose tissue, such as TNF-α and IL-6." (PMID 22174491, 2011). "Resistin expression is stimulated by TNFα and IL-6, both of which are increased in obesity, which offers an explanation for an increased level of resistin in obesity." (PMID 21410966, 2011). "TNF-α and other pro-inflammatory molecules in WAT have been implicated in the development and maintenance of obesity-induced adipose tissue inflammation." (PMID 21810260, 2011). "In animal models of diet-induced and genetic obesity increased production of IL-1, IL-6, TNF-α and Toll-like receptor (TLR) signaling in adipose tissue has also been reported." (PMID 22115311, 2011). "The detection of enhanced expression of Tumor Necrosis Factor-α [TNF- α], a prototypical inflammatory cytokine, in adipose tissue in obese mice provided first clues to presence of inflammation in obesity." (PMID 22035457, 2011). "Apparent increases in plasma concentrations of proinflammatory cytokines, including TNF-α, seem to be seen in subjects with obesity and insulin resistance." (PMID 21816064, 2011). "In models of diet-induced obesity and genetic obesity, the adipose tissue has increased expression of proinflammatory cytokines, such as TNF-α, IL-1, and IL-6." (PMID 21352586, 2011). "Obesity is also characterized by the existence of a global inflammatory state, with raised levels of circulating pro-inflammatory cytokines such as TNF-a, C-reactive protein, and IL-6, as well as a reduction in anti-inflammatory cytokines such as adiponectin." (PMID 22087859, 2011). "The increase in TNFα expression induces the production of ROS, resulting in endothelial dysfunction in obesity and obesity-related disorders such as hypertension, atherosclerosis and type 2 diabetes." (PMID 21410966, 2011). "Recent in vivo data in dietary and genetically obese mouse models demonstrated obesity-related liver inflammation and subsequent release of IL-6 and TNFα." (PMID 21081932, 2011).
Obesity (continued). "Biomarkers of inflammation, such as TNF-α, interleukin (IL)-6, monocyte chemoattractant protein-1 (MCP-1, CCL2), and C-reactive protein, are increased in obesity, associated with insulin resistance, and predict the development of type 2 diabetes." (PMID 21589925, 2011). "TNF expression was found to be increased in the adipose tissues of experimental animal models of obesity and type 2 diabetes." (PMID 21960997, 2011). "It is well known that high-fat diets or obesity result in the activation of NF- kappaB, leading to over-expression of its target genes such as IL-6, iNOS, TNF alpha." (PMID 21999347, 2011). "For example, in obese Zucker rats, the beneficial effect of exercise training on obesity and diabetes has been linked to anti-inflammatory mechanisms, with improvements in the circulating levels of CRP, adiponectin, IL-6, and TNF-α." (PMID 21599899, 2011). "Increased adipose tissue expression of TNFα mRNA has been reported in different rodent models of obesity as well as in clinical studies involving obese patients." (PMID 21410966, 2011). "Other genes involved in the development of obesity, such as leptin and TNF-alpha, have been found to be regulated by epigenetic mechanisms influences by the diet or obesity." (PMID 20534152, 2010). "Correlations persist when we analyzed only mice on HF diet, suggesting that the levels of ileal TNF-α are significantly correlated with magnitude of HF-induced weight gain and obesity." (PMID 20808947, 2010). "Adipose tissue macrophages (ATMs) are proved to be predominantly responsible for the elevated production of TNF-α and IL-6 during obesity." (PMID 21403905, 2010). "In obese diabetic KK-Ay mice, dietary dehydroabietic acid suppressed obesity-associated elevation of circular MCP-1 and TNF-α levels and their mRNA expressions in white adipose tissues." (PMID 20613991, 2010). "The impact of chronic TNFα on γδ T cells was reversible, suggesting that therapeutic strategies targeting the inflammatory environment and γδ T cell dysfunction may provide additional treatments for complications associated with obesity, metabolic disease and type 2 diabetes." (PMID 20625397, 2010). "It is well known that overproduction of TNF-α by macrophages in adipose tissue is an important feature of obesity which is thought to contribute significantly to the development of insulin resistance." (PMID 20808947, 2010). "Some make strange bedfellows (anti-TNF antibody and recombinant TNF, oxidants and anti-oxidants, starvation and obesity)." (PMID 19932638, 2010). "A significant improvement in skin γδ T cell function at the wound site suggests that chronic inflammatory conditions, specifically in the form of TNFα, contributes to skin γδ T cell hyporesponsiveness to in vivo wounding in obesity and metabolic disease." (PMID 20625397, 2010). "The proinflammatory cytokines TNF-α and IL-6 play important roles in obesity and the evolution of the disease." (PMID 20300479, 2010). "As in aging, fat tissue adipogenic transcription factor expression is decreased in obesity, and inflammatory mediators, including TNFα and IL-6, are increased." (PMID 20701600, 2010). "Obesity and smoking increase the expression of proinflammatory cytokines, including IL-1, IL-6 and TNFα." (PMID 20646281, 2010). "Expression and secretion of TNF-α increases with obesity and correlates positively with body mass index." (PMID 20825686, 2010). "Both TNF-α and JNK are implicated in inflammation-induced impairment of insulin signalling in obesity." (PMID 20508722, 2010). "Increased plasma TNFα levels correlate with obesity and insulin resistance in both humans and animals." (PMID 20625397, 2010). "Our data demonstrate that obesity is linked to increased adipose tissue expressions of CD68 and TNF-α, and that both, CD68 and TNF-α expressions predict insulin sensitivity independently of known confounders." (PMID 21197447, 2010).
Obesity (continued). "The rare allele of PPARG SNP rs3856806 has been linked with not only coronary artery disease progression, but also with pro-inflammatory cytokines (MMP9 and TNFα), plasma homocysteine levels, and obesity." (PMID 20426853, 2010). "In the nvA(H1N1)-ARDS group, obesity and lymphocytopenia were more common and IP-10, interleukin (IL)-12, IL-15, tumor necrosis factor (TNF)α, IL-6, IL-8 and IL-9 were significantly increased versus control." (PMID 21062445, 2010). "Several studies suggest that TNF-α and IL-6 are both involved in obesity-related insulin resistance and that TNF-α is one of the most important mediators of inflammation." (PMID 20825686, 2010). "The pro-inflammation cytokines such as TNF-α and IL-6 have been demonstrated to mediated insulin resistance as a result of obesity in many rodent obesity models." (PMID 20107539, 2009). "Tumor necrosis alpha (TNF-α) and interleukin 6 (IL-6), pro-inflammatory cytokines produced mainly by adipocytes and macrophages but also by muscle cells, are up-regulated in obesity." (PMID 19333447, 2009). "Obesity is related to a condition of chronic inflammation characterised by abnormal production of inflammatory cytokines with local effects e.g. TNFα or systemic effects e.g. IL-6, that can contribute to the pathogenesis of malignant diseases." (PMID 20030801, 2009). "Type 2 diabetes and obesity have characteristics of inflammatory conditions with increased blood levels of pro-inflammatory cytokines, such as interleukin (IL)-6, IL-1 and TNF-α, which attenuate insulin receptor signaling." (PMID 19114996, 2008). "Obesity leads to elevated production of pro-inflammatory molecules such as TNF-α, IL-6, IL-1β, and MCP-1 in experimental murine models and in humans, notably in adipose tissue." (PMID 18773087, 2008). "The results from this study demonstrate that this transgenic line is a valuable model for the study of TNFα role in disease progression in multiple therapeutic areas including metabolism, obesity, bone homeostasis and male sexual health." (PMID 18070349, 2007). "In vivo, under conditions of obesity, hepatocytes are simultaneously exposed to elevated FFAs and TNF-α." (PMID 17498300, 2007). "Plasma levels of CRP, TNF-α, and IL-6, which are markers of inflammation, are elevated in obesity, insulin resistance, essential hypertension, type 2 diabetes, and CHD both before and after the onset of these diseases." (PMID 18078524, 2007). "Inactivation of the endogenous TNFα gene and its two cognate receptors have demonstrated its role in inflammation as well as obesity." (PMID 18070349, 2007). "Circulating CRP levels are suggested to relate to adipose derived mediators such as leptin and TNFα, and positively correlate with measures of obesity in otherwise healthy adults." (PMID 16965635, 2006). "Circulating levels of TNF alpha show a coordinated increase with obesity during the course of gestational diabetes, and at a physiological level, this adipocytokine alters insulin signal transduction and secretion." (PMID 16965635, 2006). "Data about plasma TNFα receptors as determinants of total and LDL-cholesterol levels and about impact of obesity on the relationships between TNFα system and plasma lipids remain controversial." (PMID 16803616, 2006). "TNFα is also a regulator of lipid metabolism, however, data about impact of obesity on the relationships between TNFα and plasma lipids remain controversial." (PMID 16803616, 2006). "Obesity can induce a state of leptin and insulin resistance, chronic low-grade inflammation, and increased leptin, tumour necrosis factor (TNF)-α, IL-6 and C reactive protein serum levels." (PMID 16160698, 2005). "Several investigators have also reported increased plasma levels of TNF-α in genetic models of obesity." (PMID 15813957, 2005).
Obesity (continued). "In general, the G2 subgroups with obesity showed higher levels of pro-inflammatory cytokines IL-1β, IL-6, IFN-γ, and TNF-α than the respective G1 subgroups, and also an association of CMI in favor of a pro-inflammatory systemic status, particularly in the older women group." (PMID 41602164, 2026). "Notably, in obesity, elevated TNF levels in WAT reduce β3‐AR expression in adipose tissue, leading to catecholamine resistance in WAT." (PMID 41508774, 2026). "In obesity, the infiltration of M1 macrophages in visceral adipose tissue increases, and the secretion of proinflammatory factors such as TNF-α may be regulated by the cAMP/EPAC – ST2 pathway." (PMID 41503874, 2026). "Therefore, we conducted a meta-analysis to examine the role of HIT on pro-inflammatory cytokines including C-reactive protein (CRP), interleukin 6 (IL-6), and tumor necrosis factor-alpha (TNF-α) in children with overweight/obesity." (PMID 41590696, 2026). "In obesity, there is a pronounced shift toward M1-like macrophage polarization in adipose tissue-evidenced by increased infiltration of TNF-α, IL-6, and monocyte chemoattractant protein-1 (MCP-1)-secreting macrophages-contributing to chronic inflammation and insulin resistance." (PMID 41556049, 2026). "Chronic inflammation from obesity is closely related to oxidative stress: oxidative stress in adipocytes has been found to promote insulin resistance and enhance local release of IL-6 and TNF-α that aggravate systemic inflammation." (PMID 41590667, 2026). "In addition, higher levels of IFN-γ/IL-10 and TNF-α/IL-10 ratios were found in the G2 group (older men) with obesity than in the G1 group (older men) with normal weight." (PMID 41602164, 2026). "Notably, TRPV4 knockout mice exhibited elevated thermogenic gene expression in adipose tissue, attenuated HFD-induced obesity, and decreased levels of inflammatory cytokines such as TNF-α and IL-6." (PMID 40076916, 2025). "Indeed, obesity is characterized by chronic low-grade systemic inflammation, mediated primarily by pro-inflammatory markers (e.g., TNF-α) involved in the pathogenesis of insulin resistance and metabolic disorders." (PMID 40526637, 2025). "Similarly to IL-6, TNF-α is a synonym of inflammation and has even been considered the link between insulin resistance and obesity." (PMID 41515940, 2025). "Obesity-related cytokines (such as TNF-α, IL-6) may inhibit the HPG axis and impair Leydig cell function, further decreasing testosterone secretion." (PMID 40162320, 2025). "Obesity and hyperglycemia heighten TNF levels, creating a pro-inflammatory milieu." (PMID 40547917, 2025). "In obesity, elevated levels of TNF-α and IL-6 indicate low-grade chronic inflammation." (PMID 41010046, 2025). "Moreover, advanced chemoattraction and migration of monocytes, their subsequent polarization into inflammatory macrophage phenotypes, and secretion of IL‐1ꞵ, IL‐6, and TNF‐α are also extensively observed to occur via LTB4 in obesity and from adipose tissue." (PMID 39943721, 2025). "We hypothesized that TNF-α -308 G/A polymorphism influences insulin levels and HOMA-IR in adults with obesity, and that this effect may be modified by dietary antioxidant intake." (PMID 40732969, 2025). "↓ NO secretion; ↓ TNF-α, a potential link to higher cancer and allergy risks in obesity." (PMID 41409275, 2025). "The induction of obesity (group 2) led to a significant increase in all monitored inflammatory interleukins compared to the control group (group 1), as observed for IL-1β, IL-6, IL-8, TNF-α, and C-reactive protein, with p < 0.0001 in all cases." (PMID 40565191, 2025). "Obesity is also believed to affect treatment response in PsA and AxSpA by inducing a chronic low-grade inflammatory state through inflammatory mediators such as TNF-alpha and interleukin-6." (PMID 39150473, 2025).
Obesity (continued). "Regarding the effect of inflammation on telomere length values in obesity, the increase in BMI seems to trigger the increased secretion of inflammatory mediators, including fibrinogen, C-reactive protein (CRP), IL-6, and TNF-α, which in turn cause accelerated telomere shortening." (PMID 40566527, 2025). "Moreover, pro-inflammatory cytokines can contribute to skeletal muscle disorders, such as sarcopenia, presenting similar elevated inflammatory markers as obesity, like interleukin-1β (IL-1β), IL-6 and tumor necrosis factor alpha (TNF-α)." (PMID 41141350, 2025). "Obesity induces a chronic low-grade systemic inflammatory state, wherein adipose tissue dysfunction leads to abnormal secretion of adipokines (e.g., leptin and adiponectin) and pro-inflammatory cytokines such as TNF-α, IL-6, and IL-1β." (PMID 41305576, 2025). "Thus, in obesity, TNF-α increases adipokine production, mediated by enhanced NF-κB pathway activity." (PMID 40565251, 2025). "Additionally, TNF-α inhibitors have been tested to attenuate the inflammatory burden in obesity and improve insulin sensitivity and prevent progression of metabolic diseases." (PMID 40013194, 2025). "Moreover, elevated levels of TNF-α stimulate the generation of collagen and extracellular matrix protein, and IL-18 is a key mediator linking obesity to systemic inflammation and nephropathy." (PMID 40703753, 2025). "Serum concentrations of TNF-α were below the minimum limit detectable by the method used in 95% (38/40) of the eutrophic individuals, 93.8% (61/65) of overweight individuals, and 95.8% (92/95) of the individuals with obesity." (PMID 40359199, 2025). "Additionally, obesity promotes chronic inflammation, with adipose tissue acting as a source of pro-inflammatory cytokines such as TNF-α, IL-6, and IL-1β, which exacerbate lipid deposition in the liver." (PMID 40551780, 2025). "The visceral adipose tissue is the main contributor to systemic inflammation in obesity, as it can produce and secrete a greater quantity of pro-inflammatory cytokines, such as leptin, adiponectin, interleukin 6, and tumor necrosis factor-α, which is compared to subcutaneous fat." (PMID 40655405, 2025). "For TNF, myeloid-specific silencing did not alter obesity-associated metabolic dysfunction despite lower circulating and tissue levels of the cytokine." (PMID 40553147, 2025). "However, there is evidence suggesting that the low levels of inflammation observed in the obesity paradox, particularly TNF released from adipose tissue, is responsible for the improved cardiac function." (PMID 41334452, 2025). "Therefore, the intervention composition constitutes a promising safe and effective strategy for diminishing pro-inflammatory cytokines IL-1β and TNF-α in chronic inflammatory conditions, such as overweight/pre-obesity." (PMID 40430061, 2025). "However, obesity can contribute to IR over time, further increasing inflammatory markers such as TNF-α, IL-6, IL-1β, IL-18, and MCP-1." (PMID 40218960, 2025). "Although anti-TNF-α antibody therapy may play a role in obesity-related comorbidities, the inflammatory response observed in obesity is more likely a consequence of excess adiposity rather than its primary cause." (PMID 41141350, 2025). "Among them, TNF‐α and IL‐6 serve dual roles as both inflammatory markers and adipokines, contributing to the complex relationship between inflammation, metabolic dysfunction, and obesity." (PMID 40551726, 2025). "In the obesity and diabetes groups, the levels of pro-inflammatory cytokines such as resistin, leptin, IL-6, and TNF-α were high, which might have expanded the mass of dysfunctional adipose tissue." (PMID 40095937, 2025). "Thus, we examined the direct effect of Ang 1–7 on TNF-α secretion in this obesity experimental model." (PMID 39803918, 2025).